SLC45A1 (solute carrier family 45 member 1)
Description:
Neuron-specific proton-associated hexose transporter, which mediates hexose efflux from lysosomes. Hexose efflux is required for the stability of the vacuolar ATPase (V-ATPase) complex on the lysosomal membrane.
Synonyms: PAST-A; DNB5; IDDNPF
Tractability: Antibody: UniProt predicts a signal peptide or a membrane-spanning region. PROTAC: ubiquitination databases record sites on it.
Gene: Protein-coding gene on chromosome 1 (8,318,104 to 8,344,167, forward strand). Ensembl gene ENSG00000162426.
Subcellular location: Lysosome membrane
Gene Ontology:
Molecular function: D-glucose:proton symporter activity; hexose transmembrane transporter activity; galactose:proton symporter activity; transmembrane transporter activity
Biological process: D-glucose transmembrane transport; transmembrane transport from lysosomal lumen to cytosol; galactose transmembrane transport; transmembrane transport
Cellular component: lysosomal membrane; membrane
Genetic constraint (gnomAD): Loss-of-function variants: 28 observed, 55.23 expected, observed/expected ratio (o/e) 0.51, 90% interval 0.38 to 0.69. The upper end of that interval is the gene's LOEUF score, 0.69, which puts it in group 2 of 6, group 1 being the genes least tolerant of losing a copy. Missense variants: 809 observed, 1,053 expected, observed/expected ratio (o/e) 0.77, 90% interval 0.72 to 0.81. Synonymous variants: 456 observed, 480.46 expected, observed/expected ratio (o/e) 0.95, 90% interval 0.88 to 1.03.
Homologues: Orthologues: macaque SLC45A1 (99% identical), mouse Slc45a1 (91% identical), rat Slc45a1 (91% identical), chimpanzee SLC45A1 (90% identical), rabbit SLC45A1 (89% identical), pig SLC45A1 (89% identical), dog SLC45A1 (89% identical), guinea pig SLC45A1 (82% identical), tropical clawed frog slc45a1 (76% identical), zebrafish slc45a1 (68% identical), Drosophila melanogaster lovit (26% identical), Drosophila melanogaster Slc45-1 (23% identical). Paralogues in human: SLC45A4 (33% identical), SLC45A2 (29% identical), SLC45A3 (18% identical).
Diseases named in the same sentence as SLC45A1 in open-access papers:
SLC45A1 is named in the same sentence as 13 diseases in open-access papers, as found by Europe PMC text mining. Sharing a sentence is not in itself a finding about the gene and the disease. The quoted sentences say what the papers report.
Intellectual disability (3 papers, 2018 to 2021). "They concluded that autosomal-recessive mutations in SLC45A1 result in intellectual disability, movement disorder, and epilepsy." (PMID 34194475, 2021). "For example, ANK3 has been associated with mental retardation, SLC45A1 with intellectual developmental disorder, and CHI3L1 with schizophrenia, suggesting that differential methylation data may help reveal novel genetic variations that associate with AD." (PMID 32539856, 2020).
Alzheimer disease (1 paper, 2025). A progressive, neurodegenerative disease characterized by loss of function and death of nerve cells in several areas of the brain leading to loss of cognitive function such as memory and language. "In Alzheimer's disease, the hub genes TNFRSF9, LZIC, CD30, SLC45A1, GPR157, and SLC25A33 are implicated in immune regulation, cellular transport, neuronal signaling, and mitochondrial function." (PMID 40104076, 2025).
endothelial dysfunction (1 paper, 2025). In vascular diseases, endothelial dysfunction is a systemic pathological state of the endothelium (the inner lining of blood vessels) and can be broadly defined as an imbalance between vasodilating and vasoconstricting substances produced by (or acting on) the endothelium. "The top hub genes were TNFRSF9, LZIC, TNFRSF8, SLC45A1, GPR157, and SLC25A33, induced by P. gingivalis and F. nucleatum responsible for endothelial dysfunction in brain cells." (PMID 40104076, 2025). "The top hub genes identified were TNFRSF9, LZIC, TNFRSF8, SLC45A1, GPR157, and SLC25A33, which are induced by P. gingivalis and F. nucleatum and are responsible for endothelial dysfunction in brain cells." (PMID 40104076, 2025). "Similarly, our study revealed genes like TNFRSF9, LZIC, TNFRSF8, SLC45A1, GPR157, and SLC25A33 that contribute to endothelial dysfunction in brain cells due to P. gingivalis and F. nucleatum." (PMID 40104076, 2025).
neurodevelopmental disability (1 paper, 2021). "SLC45A1 is thus the second cerebral glucose transporter, in addition to GLUT1, to be involved in human disease and implicated in neurodevelopmental disability." (PMID 34194475, 2021).
tumor (2 papers, 2013 to 2024). "Our analysis identified seven tumour suppressor genes (ITGA7, SLC45A1, TPPP, SCN4A, GIPR, SOGA3 and RAB6B) and six oncogenes (SAT1, SERPINE1, UPK2, SYT12, RASAL1 and CDH3) with significant false discovery rate (FDR)-adjusted P values (q-value) of less than 0.05." (PMID 38429478, 2024).
SLC45A1 also shares sentences with these, for which no sentence is quoted: breast carcinoma (2 papers); epilepsy (2); brain tumor (1); gastric cancer (1); movement disorder (1); psoriasis (1); schizophrenia (1); type 1 diabetes (1).